CRP (C-reactive protein)
Diseases named in the same sentence as CRP in open-access papers (continued):
Sharing a sentence is not in itself a finding about the gene and the disease.
Behçet’s disease (20 papers, 2007 to 2026). "Sayin and colleagues 24 reported a 54% prevalence of the fQRS in 43 patients with Behçet’s disease, which was associated with a prolonged disease duration and elevated C-reactive protein levels." (PMID 31210764, 2019). "In conclusion, our study demonstrates that systemic inflammatory biomarkers—NLR, SII, PIV, and CRP/albumin ratio—are significantly elevated in pediatric Behçet’s disease and show strong correlations with organ-specific involvement." (PMID 41457500, 2026). "Other investigations have reported that CAR, NLR, and CRP levels correlate positively with Behçet’s Disease Current Activity Form (BDCAF) scores in adult patients, supporting their role as reliable inflammatory indicators." (PMID 41457500, 2026). "CRP, erythrocyte sedimentation rate, neutrophil to lymphocyte ratio, and platelet to lymphocyte ratio have been studied in Behçet’s disease to indicate disease activity." (PMID 39050391, 2024). "The aim of this study is to investigate the potential of C-reactive protein (CRP)/albumin (CAR) ratio as a tool for assessing the severity of Behçet’s disease." (PMID 39050391, 2024). "The CRP and albumin levels of Behçet’s disease patients who presented to our dermatology clinic over a three-year period from February 2020 to February 2022 were included, along with the identical laboratory parameters in the control group." (PMID 39050391, 2024). "Recently, ESR and CRP were mostly used to assess the clinical activity of Behcet’s disease, though the relationship between ESR and the clinical activity of the disease has been controversial." (PMID 37223587, 2023). "In patients with Behçet's disease, log leptin was correlated with BMI (r = .44, P = .001), and α1-antitrypsin was correlated with log CRP (r = .61, P = .000)." (PMID 17641728, 2007). "There was a significant difference between the patients with Behçet's disease and control group for both log leptin (P = .000) and log CRP (P = .031)." (PMID 17641728, 2007). "There was a significant difference between the patients with Behçet's disease and control group for both logarithm of leptin (P = .000) and logarithm of CRP (P = .031)." (PMID 17641728, 2007). "Syndecan-1 levels (9.6 ± 8.9 vs. 5.5 ± 3.2 ng/mL, P = .002), CRP levels (3.2 [0.3-41.7] vs. 1.2 [0.3-9.6] mg/dL, P < .001), and cIMT values (0.51 ± 0.1 vs. 0.46 ± 0.1 mm, P = .015) were significantly elevated in patients with Behçet’s disease compared to the control group." (PMID 41578772, 2025). "The levels of CRP and CAR were found to be significantly elevated in patients with Behçet’s disease compared to the control group (both p < 0.001)." (PMID 39050391, 2024). "Laboratory workup showed elevated CRP, elevated ESR, and positive pathergy test with a diagnosis of Behçet’s disease (BD)." (PMID 34945256, 2021). "A 25-year-old man was diagnosed ruptured thoracoabdominal aortic aneurysm with Behcet’s Disease according to his eye damage history, high level of ESR and C-reactive protein and the imaging result." (PMID 32807210, 2020). "Positive correlation was observed between hs-CRP and BDCAF (Behcet's disease current activity forum) index (r 0.68, P < 0.001)." (PMID 25759827, 2014). "When the disease activity of Behçet’s disease patients was classified as active or inactive, CRP, albumin, and CAR were not statistically different (p = 0.081, p = 0.771, p = 0.062, respectively)." (PMID 39050391, 2024). "In our study, patients with Behçet's disease with or without ocularinvolvement were found to have higher serum leptin and CRP levelscompared according to age-, sex-, and BMI-matched controls." (PMID 17641728, 2007). "In patients with nonocular Behçet's disease, α1-antitrypsin was correlated with log CRP (r = .56, P = .002), and log leptin was correlated with BMI (r = .052, P = .004)." (PMID 17641728, 2007).
diabetic neuropathy (20 papers, 2014 to 2025). A chronic, pathological complication associated with diabetes mellitus, where nerve damages are incurred due to diabetic microvascular injury involving small blood vessels that supply these nerves, resulting in peripheral and/or autonomic nerve dysfunction. "Inflammatory markers, including TNF-α, IL-6, and high-sensitivity CRP, show elevated levels in diabetic neuropathy but typically achieve lower diagnostic performance (AUC 0.65-0.75) compared to our NSE results (AUC 0.863)." (PMID 40755599, 2025). "Polygenic risk score for C-reactive protein showed a positive association, while that for fasting insulin showed a negative association with neuropathic pain, in individuals with diabetic polyneuropathy." (PMID 39471050, 2025). "The serum C-reactive protein level has been linked with impairments related to diabetic neuropathy in diabetic subjects." (PMID 37762893, 2023). "Raised levels of serum Hs-CRP were associated with an increased incidence of diabetic neuropathy during a median follow-up of 7.8 years." (PMID 36381804, 2022). "Moreover, the association between diabetic neuropathy and tumor necrosis factor-alpha has been suggested to be stronger than the association between C-reactive protein and diabetic neuropathy." (PMID 37762893, 2023). "Polygenic risk score for C-reactive protein (CRP, as a marker of inflammation) was positively associated (Pbinary and Pquantitative = 0.01) with neuropathic pain in diabetic polyneuropathy." (PMID 39471050, 2025). "Several epidemiological studies have also demonstrated an association between sub-clinical inflammation (CRP, IL6) and diabetic neuropathy using MNSI." (PMID 35329958, 2022). "It would also be of interest to examine the relationship of diabetic microvascular complications, such as diabetic neuropathy, with CRP elevation, but reliable information on microvascular complications was unfortunately not available in our present data." (PMID 25163828, 2014). "Elevated levels of CRP, interleukin (IL)-1, IL-6, C-X-C motif chemokine ligand 10 (CXCL10), tumor necrosis factor (TNF)-α, IL-12 (p70), IL-13, and IL-17A are associated with an increased risk of T2DM and diabetic neuropathy." (PMID 39408723, 2024). "Patients with painful diabetic neuropathy were found to have increased mRNA and blood protein levels of IL-1β, IL-2, TNF-α, CRP, and LEP, which could be associated with neuronal dysfunction." (PMID 39408723, 2024). "The relationship between the lifestyle behaviors and risk of diabetic neuropathy was mediated by cystatin C, GGT, total bilirubin, albumin, HDL-C, triglycerides, apolipoprotein A, CRP, and HbA1c with the proportion of mediation effect ranging from 3.22% to 11.35%." (PMID 36626356, 2023). "Moreover, inflammatory markers, i.e., white blood cell parameters, tumour necrosis factor-α, serum C-reactive protein (CRP), etc., have been observed to be related to diabetic neuropathy." (PMID 29598819, 2018). "Our research showed that age, course, ACR, Cr, MAU,α-MG, Tf, Ig,CRP and NLR were directly proportional to the severity of diabetic neuropathy and AGE." (PMID 35443645, 2022). "Moreover, increased C-reactive protein levels were noted in subjects with diabetic neuropathy when compared to those without diabetic neuropathy." (PMID 37762893, 2023). "On the other hand, the median height, weight, blood Hb and Htc, eGFR, serum albumin, C-reactive protein, HbA1c, fasting glucose, serum total, and LDL and HDL cholesterol levels of the patients, with and without diabetic neuropathy, were significantly different (p < 0.05 for all)." (PMID 37762893, 2023).
esophageal squamous cell carcinoma (20 papers, 2010 to 2024). Esophageal squamous cell carcinoma (ESCC) is a type of esophageal carcinoma (EC) that can affect any part of the esophagus, but is usually located in the upper or middle third. "We previously reported that the CRP 1846C>T genetic polymorphism is an independent factor associated with LN metastasis in thoracic esophageal squamous cell carcinoma." (PMID 32471425, 2020). "Previously, few reports demonstrated CRP levels to be elevated in squamous cell carcinoma of the esophagus and in adenocarcinoma and revealed that an increase in CRP levels correlated with tumor growth and metastasis." (PMID 33585190, 2020). "Overexpression of CXCL8 was related to tumor progression, metastasis, higher preoperative levels of proinflammatory cytokines, CRP, activation of exogenous coagulation factors, and poor prognosis in esophageal squamous cell carcinoma patients." (PMID 32851080, 2020). "As per the result, we concluded that the preoperative serum CRP level was an independent prognostic factor for patients with esophageal squamous cell carcinoma, a finding that is consistent with some previous reports." (PMID 31533862, 2019). "A high preoperative CRP level (> 5.0 mg/mL) predicts worse survival prognosis in patients who have undergone curative resection for esophageal squamous cell cancer." (PMID 31533862, 2019). "The present study aimed to test the relationship between preoperative serum CRP levels and EC-specific survival in patients who had undergone curative resection for esophageal squamous cell cancer." (PMID 31533862, 2019). "This study found that a CRP level exceeding 4.0 mg/dl on POD 4 was useful for predicting SICs in esophageal squamous cell carcinoma patients who received radical esophagectomy with perioperative steroid therapy and ERAS care." (PMID 29202716, 2017). "The present study was to establish a prognostic indicator based on preoperative fibrinogen and C-reactive protein (CRP) (FC score) in esophageal squamous cell carcinoma (ESCC)." (PMID 27517497, 2016). "The CRP/Alb ratio is a novel but promising inflammation-based prognostic score in esophageal squamous cell carcinoma." (PMID 25934640, 2015). "This study was designed to investigate the prognostic value of the C-reactive protein/albumin (CRP/Alb) ratio in esophageal squamous cell carcinoma." (PMID 25934640, 2015). "It is also of interest that similar to CRP, circulating midkine and IL-8 have been found to reflect lymph node involvement in esophageal squamous cell carcinoma." (PMID 20920199, 2010). "Furthermore, the preoperative CRP level can also play the same role in patients with small carcinoma of the esophagus or esophageal adenocarcinoma and in patients with early stage esophageal squamous cell carcinoma." (PMID 31533862, 2019). "The present study examined whether CRP levels can predict SICs in 117 advanced esophageal squamous cell carcinoma patients who received neoadjuvant chemotherapy followed by curative resection with perioperative steroid therapy and ERAS care." (PMID 29202716, 2017). "This study tested the relationship between preoperative serum C-reactive protein (CRP) levels and cancer-specific prognosis in patients with esophageal squamous cell carcinoma who have undergone curative resection." (PMID 31533862, 2019). "A novel index combined with inflammatory and nutritional biomarkers, named C-reactive protein (CRP) to prealbumin (PALB) ratio (CPR), was initially reported to predict the prognosis in resectable esophageal squamous cell carcinoma (ESCC)." (PMID 31379941, 2019). "We initially proposed a useful and novel prognostic model, named CCS [Combination of c-reactive protein (CRP) and squamous cell carcinoma antigen (SCC)], for predicting the postoperative survival in patients with esophageal squamous cell carcinoma (ESCC)." (PMID 28968977, 2017).
esophageal squamous cell carcinoma (continued). "In the current study, we proposed a novel inflammation-based prognostic score, named c-reactive protein/prognostic nutritional index ratio (CRP/PNI ratio), for predicting the prognosis for patients with resectable esophageal squamous cell carcinoma (ESCC)." (PMID 27557504, 2016).
juvenile idiopathic arthritis (20 papers, 2014 to 2026). Juvenile idiopathic arthritis (JIA) is the term used to describe a group of inflammatory articular disorders of unknown cause that begin before the age of 16 and last over 6 weeks. "Inflammation markers (C-reactive protein and erythrocyte sedimentation rate), number of active joints, Juvenile Arthritis Disease Activity Score (JADAS 10), were assessed at every observation point to define disease activity." (PMID 37848930, 2023). "As far as CRP is concerned, paralleling what reported in systemic onset juvenile arthritis, we observed that higher CRP, at the time of diagnosis, predicted mortality during the follow-up." (PMID 32645077, 2020). "Additionally, workup labs including normal complete blood count (CBC), ESR/CRP, and joint fluid analysis supported the exclusion of infection and malignancy, while raising suspicion for juvenile idiopathic arthritis." (PMID 40964590, 2025). "JIA, juvenile idiopathic arthritis; RF: rheumatoid factor; CRP: C-reactive protein; ESR: erythrocyte sedimentation rate; CHAQ: Childhood Health Assessment Questionnaire; ETN: etanercept; MTX: methotrexate; LEF: leflunomide; DMARDs: disease-modifying antirheumatic drugs." (PMID 31778437, 2019). "JIA: juvenile idiopathic arthritis, ESR: erythrocyte sedimentation rate, IQR: interquartile range, CRP: C-reactive protein, ANA: antinuclear antibody." (PMID 36694509, 2022). "Baseline CRP/ESR and TJC28 are more generic predictors for response, shown to be associated with TCZ response in RA patients (CRP/ESR) and with etanercept response (TJC28) in juvenile idiopathic arthritis (JIA) patients." (PMID 33466633, 2021). "An absence of effect of RUSF-v containing daily chloroquine on C-reactive protein concentration does not support an anti-inflammatory effect of chloroquine, for which it has been used in conditions such as juvenile arthritis at similar doses." (PMID 29548623, 2018). "C-reactive protein (CRP) and erythrocyte sedimentation rate (ESR) are used to assess disease activity in juvenile idiopathic arthritis (JIA)." (PMID 38962573, 2024).
mucositis (20 papers, 2009 to 2025). Mucositis is inflammation and damage of the mucous membranes lining the mouth and other parts of the gastrointestinal (GI) tract. "On the other hand, high CRP levels and low citrulline concentrations were associated with an increased abundance of Enterococcus and maximum mucositis severity and inflammation." (PMID 34638430, 2021). "Alpha diversity was decreased until day +22, and was associated with a low plasma citrulline and a high CRP level during mucositis episodes." (PMID 34638430, 2021). "In their study, the risk of mucositis and clinical sequelae (e.g., C-reactive protein) seemed to be enhanced by chlorhexidine mouth rinse, although the counts of microorganisms on the oral mucous membranes were significantly reduced." (PMID 19589149, 2009). "Additionally, C-reactive protein (CRP) was elevated in 79% of the cases, serving as a biomarker of systemic inflammation, consistent with the inflammatory processes associated with mucositis." (PMID 40416099, 2025). "Therefore, it would be of interest--not only in mucositis patients, but also in precancerous lesions that are associated with inflammation, like erosive lichen--to investigate the relation between inflammatory markers like CRP and WBC counts." (PMID 21352591, 2011). "CRP levels measured on the day oral mucositis reached its peak also showed a reciprocal correlation with the mucositis grade (p < 0.001)." (PMID 41002684, 2025). "For individuals with low-grade mucositis, median CRP values on the day of the highest OM score were approximately around 7 mg/L." (PMID 41002684, 2025). "Owing to this, CRP levels can be elevated during mucositis, often peaking alongside the most pronounced stages of OM or even in the presence of secondary infection." (PMID 41002684, 2025). "In fact, the opposite has been observed: patients treated with a CHG-based product have more problems with inflammation of the oral mucous membranes, resulting in an elevated mucositis score and an increase in C-reactive protein." (PMID 36986582, 2023). "Our study is also limited by its retrospective nature that hindered the uniform collection and incorporation of clinical and laboratory variables (e.g., GI symptoms, chills/rigors, mucositis, evidence of focal infection, CRP, PCT, IL-6, IL-8) into our models." (PMID 37113346, 2023). "The next day, the patient deteriorated further, became febrile with progressive mucositis and showed severe neutropenia with increased CRP (4 mg/dL)." (PMID 34245127, 2022). "In this prospective study a graphic analysis of albumin citrulline and CRP was performed and citrulline was suggested as better biomarker for GI complications, specifically mucositis." (PMID 33488571, 2020). "Both patients with adenovirus infections had fever, mucositis and elevated levels of C-reactive protein (above 100 mg/L)." (PMID 31827202, 2019). "The elevation of CRP after treatment originates from the dental infection, mucositis or pulmonary infection." (PMID 25061977, 2014). "This may be due to the fact that elevated CRP values can occur in these patients due to other types of less serious and slower-evolving infections, as well as non-infectious causes such as mucositis or the oncological disease itself." (PMID 35740770, 2022). "Reduction of CRP (p=0.002) and α-1 acid glycoprotein (p=0.002) levels after 5 days of oral supplementation; no significant variation of inflammatory markers or mucositis incidence." (PMID 41278295, 2025).